EGFR (epidermal growth factor receptor)
Diseases named in the same sentence as EGFR in open-access papers (continued):
Sharing a sentence is not in itself a finding about the gene and the disease.
tumor (continued). "Vorinostat is a pan-histone deacetylase inhibitor (HDACi) that augments BIM expression in various types of tumor cells, however, this effect is attenuated by the high expression of anti-apoptotic proteins in EGFR-TKI resistant non-small cell lung cancer (NSCLC) cells." (PMID 29212192, 2017). "Therefore, it was expected that in the ADCC assay, where human PBMCs, antibodies and low to moderate EGFR expressing tumor cells were coincubated, the antibody combination would lead to enhanced ADCC." (PMID 28467975, 2017). "FAM83B has been implicated as a mediator of EGFR‐RAS‐MAPK‐driven oncogenic transformation, and an increase in FAM83B gene expression was also observed in different tumor types, associated with increased tumor grade and decreased patient survival." (PMID 28078827, 2017). "Even more, it importantly contributes to tumor stemness and resistance to EGFR inhibition." (PMID 28767724, 2017). "However, there are divergent findings regarding the prognostic value of EGFR and KRAS mutations in circulating tumor DNA (ctDNA)." (PMID 28430611, 2017). "If EGFR mutational testing has not been performed ahead of the first-line therapy—it is estimated that 15 to 35% of patients have insufficient tumor tissue for genotyping, patients should be considered for repeated testing before starting second-line therapy." (PMID 28243590, 2017). "As signal transduction through the EGFR results in activation of wild-type K-Ras protein, tumor cells with activating K-Ras somatic mutations are continuously active and appears to be independent of EGFR regulation." (PMID 28219375, 2017). "EGFR-positive tumours may be resistant to EGFR inhibitors, therefore screening for biomarkers that negatively predict response to anti-EGFR therapy has been suggested." (PMID 28513565, 2017). "Circulating tumor DNA (ctDNA) has been approved by the Committee for Medicinal Products for Human Use of the European Medicines Agency to assess EGFR mutation status in patients with NSCLC for whom it is not possible to obtain a tumor sample." (PMID 28496005, 2017). "We hypothesize that tumor accessibility is an important factor in treatment success of the EGFR targeting drug." (PMID 27965472, 2017). "EGFR expression was also clearly increased in the liver as a result of tumour implantation." (PMID 28393839, 2017). "Seventeen (30.4%) out of 56 tumours analysed showed positive immunoreactivity to EGFR." (PMID 28320414, 2017). "In conclusion, molecular characteristics of tumor cells (EGFR in cancer cell membranes) and tumor microenvironments (VEGF in the extracellular matrix) could be simultaneously investigated when performing a colonoscopy." (PMID 28432289, 2017). "Furthermore, CYTOR contributed to cell proliferation in vitro and tumor growth in vivo via EGFR-mediated PI3K/AKT pathway." (PMID 29108264, 2017). "Inhibition of the EGFR/HER2 signaling pathway, particularly of downstream PI3K activity, suppressed PD-L1 and release of cytokines, suggesting that EGFR/HER2 inhibition may create a more favorable milieu for tumor immunotherapy." (PMID 28969039, 2017). "In order to determine new prognostic factors in these kinds of tumours we analysed the relationship between relapse-free survival (RFS) and molecular factors including MSI status, hMLH-1/hMSH-2 expression, EGFR catalytic domain mutations and EGFR expression." (PMID 28320414, 2017). "PET/CT with this tracer showed EGFR-specific and sensitive tumour localization in xenografted mice." (PMID 28597119, 2017). "However, considering that there are multiple mechanisms of primary and acquired resistance to EGFR inhibitors, we focused on dissecting molecular pathways of EGFR inhibition to find alternative or complementary strategies for increasing tumour responsiveness." (PMID 31093349, 2017).
tumor (continued). "Furthermore, we unraveled a novel mechanism that connects the proximity of macrophages to tumour cells with the EGFR signal output and we have shown that macrophages can regulate oncogenic signalling via iNOS induction." (PMID 28166195, 2017). "Though an increase in NK cell cytotoxicity was observed when tumor target cells were coated with the anti-EGFR mAb cetuximab, reflecting a capacity for ADCC, cytotoxicity was still significantly lower (both before and after chemotherapy) than that observed in healthy controls." (PMID 28220124, 2017). "To identify this resistance mechanism we isolated and clonally expanded tumor cell isolates that gained the ability to grow despite inhibition of oncogenic signaling mediated by epidermal growth factor (EGFR/HER2) and downstream protein kinase (MAPK or AKT) signaling." (PMID 28460441, 2017). "The EGFR blockade achieved tumour growth inhibition >50% for one third of the xenografts." (PMID 28186126, 2017). "Finally, like BAPN or genetic ablation of LOX, CCT365623 downregulates MATN2 and inhibits EGFR plasma membrane localization in tumours, and it suppresses tumour growth and metastasis in mice." (PMID 28416796, 2017). "However, current therapy options are limited to chemotherapy, with the addition of anti-EGFR antibodies for patients with RAS wild-type tumours." (PMID 28972570, 2017). "Additionally, having membranes of tumor cells labeled with EGFR-GFP in our experimental system allowed clear separation of tumor boundaries from the surrounding mouse tissue and stroma." (PMID 29268862, 2017). "The differences in SUVmax and serum levels of tumor markers between different EGFR mutation statues were both non-significant." (PMID 28877268, 2017). "In addition, YM155 has many functions and inhibits at least EGFR and survivin, thus serving as an anti-tumor agent." (PMID 28787001, 2017). "The epidermal growth factor receptor (EGFR) has a crucial role in aggressive tumor growth." (PMID 28700691, 2017). "In summary, our study indicated that ddPCR can be used for plasma cfDNA EGFR mutation detection, and plasma cfDNA EGFR mutation analysis could be an effective supplemental test for tumor-tissue EGFR M- patients." (PMID 28052016, 2017). "The combination mechanism of bevacizumab may enhance the anti-tumor activity of EGFR TKIs and perhaps increase intratumoral concentration of EGFR TKIs to partially reverse intrinsic resistance." (PMID 29088904, 2017). "The T790M EGFR mutation was detected in CTCs in four patients (57%) and in tumor samples from five patients (71% (one patient did not have detectable CTCs)." (PMID 29312651, 2017). "Subsequently, EGFR-TKIs were administered to 114 of these patients, 80 of whom were positive for EGFR TKI-sensitizing mutations (Exon 19 del and Exon 21 L858R) (EGFR M+) in tumor tissue, and 34 of whom were negative (EGFR M-)." (PMID 28052016, 2017). "When BEAM was used to analyze the plasma EGFR mutations, the sensitivity was 70% and the false-negative rate was 30% in plasma genotyping for T790M compared with tumor genotyping." (PMID 28099915, 2017). "Furthermore, VEGFR and EGFR share common downstream signalings, and have direct and indirect auxo-action on the development of tumor and angiogenesis." (PMID 28086226, 2017). "Tumor cells with high level of EGFR undergo apoptosis upon treatment with TGFα-PE38." (PMID 28473665, 2017). "KRAS gene at 12p12 has long been studied as a crucial oncogene, and tumor cells with wild‐type KRAS may benefit from anti‐EGFR therapy." (PMID 28504856, 2017). "On the basis of the cftDNA data of the present work it can be speculated that either EGFR amplification could be a frequent finding in these patients, or that p.T790M is present in a minority of cells of the tumor cell population after TKI failure or both." (PMID 29156777, 2017).
tumor (continued). "The clusters were significantly associated with tumor histological grade of differentiation (Fisher’s exact test p value = 0.009) but none of other variables (age at diagnosis, gender, tumor stage, cell subtype and EGFR mutation status)." (PMID 29137177, 2017). "Some clinical researches provided the suggestions that the status of some bio markers may alter between the primary tumor and the corresponding distant metastatic sites, including epidermal growth factor receptor (EGFR), multidrug resistance (MDR), and HER-2." (PMID 28404895, 2017). "Particularly, several in vitro experiments indicated that AvidinOX-anchored anti-EGFR biotinylated antibodies like biotinylated Cetuximab (bCet) or Panitumumab (bPan), exert much higher inhibitory activity against EGFR+ tumor cells compared to their original version." (PMID 28186982, 2017). "It was highlighted that dietary cranberry would beneficially modulate colonic inflammation and caecal SCFAs, inhibit activation of EGFR signaling and regulate proliferation and apoptosis of tumour cells possibly due to the fermentable fibre components and phenolic compounds in berry." (PMID 29228651, 2017). "Few studies compared EGFR expression in tumor tissue and sEGFR." (PMID 29229933, 2017). "Many tumor cells express high levels of epidermal growth factor receptor (EGFR)." (PMID 28473665, 2017). "Moreover, continuous EGFR signaling from late endosomes was shown to contribute to sustained downstream AKT and STAT3 activation and the endosomal accumulation of the activated EGFR increased tumor cell survival." (PMID 29176966, 2017). "We performed IHC staining of EGFR in tissue microarrays including nearly 500 patient tumor samples." (PMID 28740577, 2017). "In this review the role of the EGFR for the functioning of the immune system is discussed, alongside how EGFR antagonist treatment could be impacting tumor growth by blocking macrophage and FoxP3-expressing regulatory CD4+ T cell function." (PMID 28970798, 2017). "Besides, our studies on the previous generation of anti-EGFR Affibody molecules demonstrated that residualizing radiometal labels provide appreciably better tumour retention of the radionuclide at 24 h after injection." (PMID 28729680, 2017). "Responses were seen in only 2 patients with EGFR mutant tumours." (PMID 29050231, 2017). "The multivariate analysis showed that patients with lower MTV (MTV≤11.0 cm3, p=0.001) who were non-smokers (p=0.037) and had a peripheral tumor location (p=0.033) were more likely to have EGFR mutations." (PMID 28422710, 2017). "Finally, we examined the effect of BLM delivery by sonoporation with EGFR-MBs on in vivo tumor growth in KSN/slc nude mice." (PMID 28938010, 2017). "In cancer cells, deregulation of EGFR trafficking has a variety of effects on tumor progression." (PMID 29084952, 2017). "To assess whether PGE2 was able to induce EGFR nuclear translocation, we treated tumor cells for the same time points with PGE2 1 μM." (PMID 28415726, 2017). "Finally, according to our trend analysis of tumour volume changes, the anti-tumour effects of the Anti-EGFR-CIL-miR-135a group were strongest, with an inhibitory rate of 60%, which was higher than that of the other groups." (PMID 28729631, 2017). "We evaluated whether metabolic tumor volume (MTV), a parameter measured by [18F] fluorodeoxyglucose positron emission tomography/computed tomography (PET/CT) might help predict EGFR mutation status in NSCLC." (PMID 28422710, 2017). "Gefitinib also displayed anti-tumor activity in these two models with EGFR gene amplification." (PMID 28881608, 2017). "Low levels of expression of AREG and EREG may characterize a tumor that is less dependent on EGFR and, therefore, particularly prone to develop resistance to EGFR inhibitors." (PMID 28002810, 2017).
tumor (continued). "On the basis of our data, we propose a model whereby LOX activates the secreted protease HTRA1, which inhibits TGFβ1 signalling, causing increased expression of the EGF-like domain containing protein MATN2, which then enhances EGFR signalling to drive tumour growth and metastasis." (PMID 28416796, 2017). "However, EGFR inhibitors demonstrated poorer anti-tumor effect in cell lines with higher expression of STs (right side of heat-map)." (PMID 28423672, 2017). "In addition, 5 discordant cases were found between the tumor tissue and plasma genotyping, in which ARMS-Plus correctly identified the EGFR mutant alleles in 4 patients, while ddPCR was only correct in one case." (PMID 29340107, 2017). "EGFR mutations were evaluated using FDG-PET and serum levels of tumor markers." (PMID 28877268, 2017). "Here again, tumor cells with activating K-Ras somatic mutations are continuously active and appears to be independent of EGFR regulation." (PMID 28219375, 2017). "The maximum standardized uptake value (SUVmax) of FDG uptake in lung lesions was a predictive factor of the EGFR mutations (p = 0.029), while metabolic tumor volume and total lesion glycolysis were not predictive." (PMID 28881771, 2017). "In September 2014, the Committee for Medicinal Products for Human Use at the European Medicines Agency approved the use of ctDNA to assess the status of EGFR mutations when selecting EGFR-TKIs for patients in whom obtaining a tumor sample is not an option." (PMID 28099915, 2017). "However, almost all patients suffered from tumor progression and inevitably became resistant to EGFR-TKIs within 8-12 months (a phenomenon referred to as acquired resistance)." (PMID 28705152, 2017). "This facilitated targeting of Ad to EGFR-upregulated tumor cells." (PMID 28944214, 2017). "Several lines of evidence suggested that EGFR targeted therapy could induce cytoprotective autophagy that was related to both innate and acquired drug resistance in different tumor cell lines." (PMID 28531218, 2017). "In particular, the combination treatment of TAK-701 and gefitinib markedly reduces tumor growth in HCC827-HGF cell xenografts, a human NSCLC cell line with an activating EGFR mutation and HGF overexpression; this treatment also inhibited phosphorylation of c-MET, EGFR, ERK, and Akt." (PMID 28817103, 2017). "In addition to its intrinsic oncogenic potential the EGFR also plays an important role in evasion of tumor immunosurveillance." (PMID 28611673, 2017). "Univariate analysis demonstrated that the mutation incidence was high in female and non-smoking patients, and multivariate analysis also indicated that not smoking correlated with tumor-tissue EGFR mutation status (OR 2.487, 95% CI: 1.193-5.185, P = 0.015)." (PMID 28052016, 2017). "In contrast, an ORR of 57.1% (4/7) was observed in plasma EGFR mutation negative but tumor tissue EGFR mutation positive patients." (PMID 28829813, 2017). "A mutation hotspot was found downstream of ERRFI1, an important regulator of the EGFR pathway, which may serve as a potential tumor suppressor." (PMID 28358873, 2017). "We first investigated this hypothesis in patients carrying mutated EGFR who had been treated with EGFR‐TKI and demonstrated that RHOB tumor tissue levels predicted patient response rate to EGFR‐TKI therapy." (PMID 28003335, 2017). "This tumor was EGFR (epidermal growth factor receptor), ALK (anaplastic lymphoma kinase), KRAS (V-Ki ras2 Kirsten rat sarcoma viral oncogene homolog), ERBB2 (erb-b2 receptor tyrosine kinase 2), and B-Raf (V-raf murine sarcoma viral oncogene homolog B1) wild-types." (PMID 28915906, 2017). "Thus, we find that the greater number of subclones present in the initial tumor, the greater the benefit there is in increasing switching frequency in terms of the achieving robustness to perturbations in EGFR TKI drug concentration." (PMID 28287179, 2017).
tumor (continued). "To elucidate the effect of EGFR/HER2 signal blockade on the tumor immune microenvironment, we examined the association between PD-L1 expression and the EGFR/HER2 signaling pathway and the direct effect of EGFR/HER2 pathway inhibition on the cytokines release by tumor cells." (PMID 28969039, 2017). "Among the 93 tumor-tissue EGFR M+ patients, the median cfDNA concentration of the 57 plasma EGFR M+ patients was 11.61 ng/mL (range 1.63-406.91), while that of the 36 plasma EGFR M- patients was 7.73 ng/mL (range 1.01-29.76); this difference was statistically significant (P = 0.003)." (PMID 28052016, 2017). "Using tumor tissue EGFR mutation as the gold standard, false-negative results were found in 10 patients, including 5 with 19del, 4 with L858R and one with both 19del and L858R mutations." (PMID 29340107, 2017). "In addition, we found iNOS gene induction in macrophages that are cultured in tumour cell-conditioned media as well as an iNOS activity-dependent increase in EGFR activity in tumour cells." (PMID 28166195, 2017). "The 2016 WHO classification of CNS tumors (2016 CNS WHO) first uses molecular characteristics plus histology to define many tumor entities, such as IDH mutation and EGFR amplification, formulating a concept of how tumor diagnosis should be constructed in the molecular era." (PMID 29108264, 2017). "Tumor cells with EGFR amplification, those in the process of migration or exposed to hypoxia all have been shown to express higher levels of ZEB1 than controls and experimental studies have identified molecular mechanisms involved in ZEB1 regulation, such as PDGFRA, Wnt- or TGF-beta signaling." (PMID 28945795, 2017). "In our study, we hypothesized that tumor cells with EGFR amplification were prone to recur or metastasize." (PMID 28854970, 2017). "Our model suggests a mechanism on the level of cell dissemination characteristics that explains how targeting EGFR aberrations, or heterogeneous aberrations, might increase treatment success based on the reduction of heterogeneity within the tumour." (PMID 28800767, 2017). "Indeed, the observation that the majority of patients showed an increase in RHOB tumor expression after relapse further supports a role of RHOB in EGFR‐TKI resistance." (PMID 28003335, 2017). "Thus, our findings now provide the rationale to do so and pave the way for novel biomarker-driven clinical trials testing an EGFR-TKI plus an Akt inhibitor in appropriately selected EGFR-mutant NSCLC patients with high pAkt tumor expression." (PMID 28871105, 2017). "The epidermal growth factor receptor (EGFR) is a fatal cancer marker, and is involved with lots of intracellular pathways which promote cancer-cell proliferation, invasion, metastasis, and stimulate tumor-induced neovascularization." (PMID 27690345, 2017). "Furthermore, a significant correlation between high EGFR activity in tumour cells and macrophage-tumour cell proximity was found to in part account for the intratumoral heterogeneity in EGFR activity observed." (PMID 28166195, 2017). "This study investigated the relationship between epidermal growth factor receptor (EGFR) and Kirsten rat sarcoma viral oncogene homolog (KRAS) mutations in non-small-cell lung cancer (NSCLC) and quantitative FDG-PET/CT parameters including tumor heterogeneity." (PMID 28881771, 2017). "In summary, our findings suggest that detection of EGFR mutation in cfDNA from plasma appears to be a promising and minimally invasive alternative to tumour biopsy for patients without available tissue samples." (PMID 28006816, 2017). "While these data confirm the connection between RTK inhibition and ultimate tumor prevention, the results also suggest that lapatinib may induce a broader impact on erbB-2/EGFR signaling beyond the canonical regulatory pathways." (PMID 28061785, 2017).